NLRP13 (NLR family pyrin domain containing 13)
Description:
Involved in inflammation.
Synonyms: NALP13; NOD14; PAN13; CLR19.7
Tractability: PROTAC: its protein half-life has been measured.
Gene: Protein-coding gene on chromosome 19 (55,891,699 to 55,932,336, reverse strand). Ensembl gene ENSG00000173572.
Gene Ontology:
Biological process: regulation of inflammatory response
Cellular component: cytoplasm
Genetic constraint (gnomAD): Loss-of-function variants: 80 observed, 94.58 expected, observed/expected ratio (o/e) 0.85, 90% interval 0.7 to 1.02. The upper end of that interval is the gene's LOEUF score, 1.02, which puts it in group 4 of 6, group 1 being the genes least tolerant of losing a copy. Missense variants: 1,421 observed, 1,289.7 expected, observed/expected ratio (o/e) 1.1, 90% interval 1.05 to 1.15. Synonymous variants: 553 observed, 491.39 expected, observed/expected ratio (o/e) 1.13, 90% interval 1.05 to 1.21.
Homologues: Orthologues: chimpanzee NLRP13 (99% identical), macaque NLRP13 (89% identical), pig NLRP13 (52% identical). Paralogues in human: NLRP14 (37% identical), NLRP5 (31% identical), NLRP8 (29% identical), NLRP2 (25% identical), NLRP7 (25% identical), NLRP12 (23% identical), NLRP3 (23% identical), NLRP11 (22% identical), NLRP4 (22% identical), NLRP9 (22% identical), NLRP1 (20% identical), NLRC3 (16% identical), and 8 more.
Diseases named in the same sentence as NLRP13 in open-access papers:
NLRP13 is named in the same sentence as 10 diseases in open-access papers, as found by Europe PMC text mining. Sharing a sentence is not in itself a finding about the gene and the disease. The quoted sentences say what the papers report.
diabetes type 2 (1 paper, 2020). "The other two variants, NLRP13 and SLCO4C1, are found to be implicated in different types of cancer, diabetes type 2, eye movement dysfunction and obesity." (PMID 32973469, 2020).
infection (2 papers, 2021). The state of being infected such as from the introduction of a foreign agent such as serum, vaccine, antigenic substance or organism. "In contrast, expression of antimicrobial molecules, including perforin (PRF1), cationic antimicrobial peptide (CAP18), and inflammasome (NLRP13), were upregulated in Mtb-SC-infected lungs at 24 h post infection." (PMID 34732811, 2021). "Interestingly, T. gondii infection upregulated the expression of NLRC4, NLRP4, NLRP8, NLRP10, NLRP11, NLRP13, and NLRP14 mRNAs at both 4 and 8 h post-infection, but NLRP4, NLRP8, NLRP10, and NLRP11 mRNAs were significantly downregulated at 8 h post-infection compared to that at 4 h post-infection." (PMID 33712075, 2021).
NLRP13 also shares sentences with these, for which no sentence is quoted: autoimmune lymphoproliferative syndrome (1 paper); cancer (1); chronic granulomatous disease (1); co-infection (1); lymphoproliferative disorders (1); Obesity (1); Omenn syndrome (1); tumor (1).